CD40 (CD40 molecule)
Diseases named in the same sentence as CD40 in open-access papers (continued):
Sharing a sentence is not in itself a finding about the gene and the disease.
tumor (continued). "Tumor cells express high levels of CD30, CD40, IRF4, CD15 and constitutively active nuclear factor kappa B (NF-κB)." (PMID 35626032, 2022). "CD40 activation licenses DCs to promote CD8+ T cell immunity, while anti-CD3 can coordinately activate T cells that are partially activated by tumor cells." (PMID 36073543, 2022). "Subsequent studies in murine models showed the ability of CD40 stimulation to achieve TME remodeling as a monotherapy, and increased tumor control was achieved when CD40 stimulation and anti-CTLA-4 and anti-PD1 were used in combination with chemotherapy." (PMID 34282297, 2022). "A previous study has reported that the promotion of CD40L/CD40 expression in GBM can induce immune stimulation and anti‐tumour responses." (PMID 35908277, 2022). "Tumor treatment with decitabine also resulted in increased levels of MHC and costimulatory molecules (CD80, CD86, and CD40) essential for DC antigen presentation function." (PMID 35992806, 2022). "CD40 agonist stimulation can also induce DC activation and change TAM polarization from an M2- to M1-like phenotype to deplete tumor stroma and provide additional immune attack on tumors." (PMID 36077755, 2022). "RECK over expression also correlated with higher protein levels of CD40/TNFRSF5 and lower levels of IL-8 protein in a SW756 derived tumor mice model." (PMID 34066355, 2021). "Macrophage activation with anti-CD40 antibodies could be combined with other macrophage-activating agents, such as, CpG-containing oligodeoxynucleotides that may act by affecting the effector functions of TAMs to convert them from the M2 pro-tumor phenotype to M1 antitumor phenotype." (PMID 34831416, 2021). "Herein, we present the technical aspects of Mannan-BAM, TLR Ligands, Anti-CD40 Antibody (MBTA) vaccine immunotherapy, an investigational therapeutic that potentially circumvents the need for in silico tumor-neoantigen enrichment." (PMID 33810617, 2021). "This was augmented by combination with anti-CD40 agonist, which further promoted intratumoral infiltration of CD8 T cells and tumor eradication in several syngeneic murine tumor models." (PMID 34868044, 2021). "The widespread expression of CD40 on different tumor types, including RCC, suggests that CD40 ligation can also influence tumor development." (PMID 34445576, 2021). "In another study, a single dose of agonistic CD40 antibody in combination with gemcitabine and nab-paclitaxel enhanced TAM activation and the clonal expansion of T-cells that facilitated tumor destruction and durable remission." (PMID 34201127, 2021). "It is interesting to examine the combination effects of OK-432 and IL-12 or upstream of IL-12, such as CD40/CD40L, on tumor progression both in vitro and in vivo." (PMID 34209347, 2021). "Combination of CD40 activating antibody and anti-PD-1/CTLA-4 resulted in tumor regression and immunological memory in KPC mice." (PMID 34290984, 2021). "IL-2/α-CD40 combination therapy has enough potential to induce the IFN-α– and NO-dependent reduction of MMP9 expression in the tumor microenvironment and diminishes the probability of metastasis development to the lung." (PMID 32902664, 2021). "Strikingly, our work further shows that this dual-targeting anti-IL-6 and pro-CD40 strategy overcomes GBM resistance to checkpoint blockade therapy, likely due to a shift of tumor immune status from immunologically cold to hot." (PMID 34103524, 2021). "The reprogramming of TAMs with anti-CD40 has also shown efficacy in increasing the intratumoral accumulation and longevity of TCR-engineered T-cells that promote tumor cell apoptosis." (PMID 34201127, 2021). "CD40/CD40L interaction partakes in both innate and adaptive anti-tumor immunity via stimulating pro-inflammatory cytokine production, including IL12 and TNF- α, the induction of ADCC, and T cell-mediated immunity and antibody production." (PMID 34944850, 2021).
tumor (continued). "Various cytokines, such as IL-13, IL-15, and IL-32, and surface proteins, including CD47, CD40, and CD28, provide the direct molecular bridge between tumor cells and adjacent cells, resulting in tumor progression." (PMID 34830466, 2021). "In terms of LUAD patients, most biomarkers, including IDO1, CTLA4, LAG3, CD40, TNFRSF18, TIGIT, and TNFSF14, were significantly increased in tumor tissues with high B cell abundance compared with that of low B cell group." (PMID 34422829, 2021). "CD40, a member of TNF receptors, is broadly expressed on immune cells like DCs, B cells as well as some tumor cells." (PMID 34372912, 2021). "Using Spearmen r ≥ 0.3 or r ≤ − 0.3 and p < 0.001 as a cut-off, we showed that CD40 is moderately co-expressed with CD40LG in the normal tissues (r = 0.44) and in the tumor microenvironment (TME, r = 0.37)." (PMID 34758832, 2021). "Gemcitabine suppresses myeloid-derived suppressor cells (MDSCs), upregulates expression of immune accessory molecules and adhesion molecules (e.g., CD80, CD86, CD40, ICAM-1), and increases tumor-specific T cell responses in a mouse model of oral cancer." (PMID 33804039, 2021). "The effects in our C57BL/6 wt mice were similar to intra-parenchymal infiltrates, perivascular clusters and necrosis as well as sALT elevation in tumor free C57BL/6 and BALB/c mice treated with 100 μg agonistic CD40 mAb." (PMID 34440067, 2021). "In contrast, TDLNs and tumor environment provides more cell–cell interaction promoting effective CD40 crosslinking through FcγRIIb and allowing for maximum potency of APX005M in the tumor itself." (PMID 33392713, 2021). "In recent years, numerous BsAbs targeting the costimulatory (e.g., OX40, CD40, 4-1BB etc.), coinhibitory pathways (PD-1, CTLA-4, TIM-3, TIGIT etc.)or tumor antigens (MUC1, MUC16) have been developed and are in preclinical and clinical investigations." (PMID 34768776, 2021). "Anti-CD40 is then administered with the intent to activate antigen-loaded APC and to trigger priming of tumor-specific T cells." (PMID 34101617, 2021). "In murine tumor models with high PD1+ T cells, CD40 agonism reversed T cell exhaustion and enhanced response to anti-PD-1 and anti-CTLA-4 immune checkpoint inhibition, suggesting a re-sensitization benefit for patients who experience resistance to ICI." (PMID 33572196, 2021). "In comparison with adjacent and precancerous tissues, we found a significant reduction of CD40+, CD27+, KLRB1+, and CCL5+ B cells (clusters 4, 9, 1, and 3, respectively) and MZB1+, DUSP1+, and CCL3+ plasma cells (clusters 5, 7, and 8) in tumor tissues." (PMID 34185431, 2021). "In these models, anti-CD40 and anti-OX40 were both shown to sensitize tumor-bearing mice to anti-PD-1/PD-L1 ICIs." (PMID 33503832, 2021). "The increased expression levels of CD40 and CD86 can promote T-cell activation and play an anti-tumor role." (PMID 34034714, 2021). "Further, activation of DC via CD40 stimulates efficient cross-presentation, which is crucial for inducing a CD8+ T cell response towards tumor antigen, both in situ tumor antigens and therapeutic vaccines." (PMID 33948686, 2021). "While xenograft models using CD40+ lymphoma cell lines have shown antitumour activity by CDX-1140, with attenuated tumour growth and increased survival, safety studies in cynomolgus macaques support the use of the antibody in humans." (PMID 33430146, 2021). "A classified ‘cold’ neuroblastoma tumor achieved complete tumor eradication upon immune stimulation with anti-CTLA-4, anti-CD40, and toll-like receptor 9 (TLR9) agonist in addition to radiation and anti-GD2-IL-2." (PMID 33803078, 2021). "Overall, our analysis evaluated B‐cell immunity in human CRC and revealed the attenuated antigen presentation and diminished antitumor immunity capacity of CD40+ and CD27+ B cells in tumor." (PMID 34185431, 2021).
tumor (continued). "We assessed stromal C4BPA, the C4BPA binding partner CD40, and the number of CD8+ tumor-infiltrating lymphocytes in resected human PDAC tissues via immunohistochemical staining." (PMID 34167573, 2021). "Mechanistically, the stimulation via CD40 rescues CD4+ T cell helper activity, promoting the generation of tumor-specific CD8+ T cells." (PMID 33671252, 2021). "Vorinostat or panobinostat, combined with immunomodulatory antibodies targeting CD40 and CD147 in mouse models of breast or colon adenocarcinoma solid tumors, induced complete tumor regressions with sustained immunological memory." (PMID 34680389, 2021). "By blocking this signal through Sirpα binding, the surface of the tumor cells is coated with the drug, allowing the CD40L side to bind to CD40 on APCs, which will lead to enhanced antigen presentation to CD8+ and CD4+ T lymphocytes and tumor cell phagocytosis." (PMID 35070956, 2021). "Poly6 treatment also enhanced expression of DC maturation markers CD40, CD80, CD86, and MHC class II molecules in tumor and draining lymph node tissues in MC38-bearing mice." (PMID 33499256, 2021). "Inhibitors of CSF1R, CCL2 and CCR2, CD47/SIRPα complex antagonists, CD40 agonist antibodies, and inhibitors of PI3Kγ and TREM2 protein are undergoing clinical evaluation for various tumor types." (PMID 34638378, 2021). "In the MB49 model, an anti-CD40 agonist antibody activates DCs and then reverses CD8+ T cell exhaustion signatures, resulting in the reduction of tumor burden and increase of survival." (PMID 34572939, 2021). "We then examine the evidence supporting an immune-based vaccine therapy that utilizes mannan-BAM, TLR Ligands, anti-CD40 antibody (MBTA) to induce both an innate and adaptive immune response to tumor cells as a potential treatment specifically for GBM." (PMID 33810617, 2021). "Comparison between the pairs of primary and recurrent tumor samples revealed that 5 genes were concordantly upregulated with a > twofold difference in expression level, including BCL10, BIRC3, CD40, TNFRSF10A and TRAF4." (PMID 34488754, 2021). "In summary, our work unravels an IL-6-regulated cellular mechanism that controls Mφ-mediated tumor immunity through IL-10 and Stat3/HIF-1α/CD40 expression." (PMID 34103524, 2021). "After examining the interplay between human dendritic and NK cells, another study reported that CD40/CD40L interaction increases the cytotoxic functions of NK cells and leads to an inhibition of tumor cell growth in many human cancers." (PMID 34686187, 2021). "In vivo studies of SL-172154 have demonstrated superior anti-tumor activity with the fusion protein over either CD47 antagonist, CD40 agonist antibody as monotherapy or the combination of the two, suggesting a synergistic role." (PMID 34944850, 2021). "The rationale for this is that prior work by others has shown synergistic antitumor action of anti-CD40 Ab and GEM in mouse models, including a transplantable PDA tumor setting." (PMID 32358491, 2020). "Bregs suppress the immune responses against HCC primarily via the CD40/CD40L mediated production of IL-10 and TGF-β, which down-regulate TNF-α that is critical for halting tumor progression." (PMID 33230233, 2020). "We also observed that VV-iPDL1/GM significantly promoted tumor-infiltrating DC maturation, as evidenced by an increased expression of MHCII, CD80, CD86, and CD40." (PMID 32170083, 2020). "Agonistic antibodies and/or RNA aptamers targeting receptors including 4-1BB, OX40, CD40, GITR, ICOS and CD28 are in pre-clinical development, and have shown anti-tumor activity in mouse models of cancer." (PMID 31959281, 2020). "Agonistic CD40 mAb treatment substantially increased the expression of IFNγ and IDO1 in tumor tissue, and their levels in individual tumors were positively correlated." (PMID 32231867, 2020). "Local irradiation with a single dose of 9 Gy increased expression of CD40 and CD86 on CD103+ DCs, suggesting maturation of Flt3L-induced tumor-residing CD103+ DCs." (PMID 33110069, 2020).
tumor (continued). "Agonistic CD40 mAb treatment increased IDO1 expression in tumor endothelial cells, resulting from increased T-cell infiltration and higher levels of IFNγ in the tumor stroma." (PMID 32231867, 2020). "In line with the proven T cell dependent anti-tumor effect, we observed a dramatic increase in the CD8/Treg ratio by the MEKi/CD40 Ab combination." (PMID 33024933, 2020). "CTLA-4 downregulates T-cell activation and inhibits its anti-tumor immune response by binding to co-stimulatory molecules on DCs (CD40, CD80, and CD86) and suppressing their ability in presenting foreign or tumor antigens." (PMID 32784928, 2020). "In AT-3 tumor-bearing mice, we found that intratumoral administration of Flt3L more effectively controlled tumor growth than systemic injection in combination with RT and in situ TLR3/CD40 stimulation." (PMID 33110069, 2020). "Combining agonistic CD40 mAb therapy with the IDO1-inhibitor epacadostat resulted in increased T-cell activation, delayed tumor growth and increased survival in B16-F10 tumors." (PMID 32231867, 2020). "Rather, macrophage depletion significantly reduced the tumor regression activity of mAbs targeting CD20, CD30, and CD40 in mice." (PMID 32121592, 2020). "As expected, the expression level of HAVCR2, CD40, SIGLEC7, CD86 genes are inversely correlated with tumor purity." (PMID 32021566, 2020). "One potential reason is that anti-PD-1 Ab, in contrast to anti-CD40 Ab treatment, lacks the capacity induce T cell infiltration and enhancing pro-inflammatory myeloid cells, such as M1 macrophages, which may be essential for T cell dependent long-term anti-tumor effects." (PMID 33024933, 2020). "More importantly, the expression of MHC I, CD40 and TAP1 in DCs in GL-261 LGALS9−/− tumor-bearing mouse CSF was significantly higher than that in DCs in GL-261 WT tumor-bearing mouse CSF." (PMID 33093453, 2020). "To further verify the critical role of Tscm in preventing tumor, we sorted the subsets of HPV16 E7 specific CD8+ memory T cells (Tem, Tcm, Tscm) from CD40 immunized mice, and, respectively transferred different memory T cells into nude mice." (PMID 32536922, 2020). "Such is the surface receptor CD40, a TNF receptor family member expressed by APCs and B cells, that stimulates cytokine expression and activation of T cells and induces tumor cell death." (PMID 31970590, 2020). "Firstly, CD40 stimulation induced long-lived HPV-specific CD8+ Tscm, which consistently differentiated into Tcm and Tem, and evoked persistent anti-tumor response." (PMID 32536922, 2020). "Incubation with PS1 siRNA-treated CAF-conditioned medium resulted in a significant increase in CD40 and CD86 levels in dendritic cells (p < 0.05), indicating an increase in their ability to present tumor antigens to other effector cell types." (PMID 32587587, 2020). "Researchers attempted to use CD40L-carrying exosomes as a stronger signal to trigger maturation of DCs by combining the features of tumor antigens in TEX and CD40L on exosomes targeting CD40 on DCs." (PMID 32983146, 2020). "This study was to investigate the role of CD40 in HPV16-specific CD8+ Tscm induction and its anti-tumor function." (PMID 32536922, 2020). "To further investigate how the DCs behaved, we analysed the presence of these cells in the tumor‐draining lymph nodes (TDLN) and observed a 3‐fold increase in number of DCs when CD40 agonist was administered." (PMID 32821382, 2020). "Potent anti-tumour responses were observed in mice by incorporating CpG-ODN and anti-CD40 agonist antibody into liposomal carriers, with elimination of systemic toxic side effects achieved by focused sequestration in the TME." (PMID 33352882, 2020). "Researchers successfully designed CD40L-carrying exosomes that possess a stronger ability to trigger maturation of DCs by integrating the features of tumor antigens in TEX, CD40/CD40L targeting DCs, and CD40 signaling." (PMID 32983146, 2020).
tumor (continued). "In a subsequent study, the same team found that the agonist of CD40 induced heavy T cell infiltration into tumours upon combination with Gem and resulted in CD4+ and/or CD8+ T cell-dependent tumour regression." (PMID 32061257, 2020). "Only upon co-culture with PBMCs we observed a CD40 upregulation upon treatment with XAV-939, highlighting a key tool in elicitation of an effective immune mediated anti-tumor response." (PMID 31277479, 2019). "The functions of these genes, namely CD40, MAP2K6, TRAF5, PI3K2R, have been reported in enhancing cell proliferation and tumor growth/metastasis." (PMID 31349612, 2019). "Therefore, we suggest that in Bhi tumors, TIL-Bs might recruit CD8+ T cells via CXCL9 and crucially contribute to the survival of the CD8+ T cells in the tumor microenvironment due to the in situ secondary costimulation employing CD40L/CD40 and TNFR/TNF superfamily signaling pathways." (PMID 31623665, 2019). "In mouse tumor models, high expression of CD40/CD154 had an anti-tumor effect, and a low level of CD40/CD154 was shown to promote tumor growth." (PMID 31708918, 2019). "CD40 expression on MDSCs has been shown to be important for suppressive activity and MDSC-mediated Treg expansion in tumor bearing mice." (PMID 31849990, 2019). "Agonistic CD40 mAb, particularly IgG1 isotype, is ideal for combination therapy due to their ability to induce ADCC, providing tumor antigens for subsequent uptake by DC." (PMID 30788290, 2019). "Increased priming was also supported by our observation of increased T cell frequency and increased expression of costimulatory molecules CD40 and CD86 on APCs in the tumor-draining lymph nodes." (PMID 31921384, 2019). "Using CD40, agonist mAbs can mimic the responses induced by CD40L, making them interesting targets in the tumour context." (PMID 31091774, 2019). "Anti-CD40/CpG activate innate immunity, mainly macrophages, while anti-CTLA-4 releases the brakes on effector T cells and can deplete CD4+ Tregs in the tumor microenvironment." (PMID 31810498, 2019). "As for HNSCC patients with tumor high stage, the expression of CD40 on APCs as well as tumor cells decreased, and the same applies the level of CD154 on T cells, while soluble CD40 increased in body fluids, representing a state of reduced immunity." (PMID 31708918, 2019). "CD40 is also an important receptor at the TAM surface, as its ligation with the CD40 ligand at the T-cell surface stimulates T-cell–based anti-tumor responses." (PMID 31547627, 2019). "Tumor DCs from wildtype mice had higher average expression of CD40 and CD80 compared to DCs from TLR9−/− mice, suggesting that host TLR9 promotes the maturation of tumor DCs." (PMID 31619293, 2019). "Flow cytometric analysis revealed that ssRNA and dual-function vector treatment significantly increased the proportion of pDCs (CD317+CD11c+B220+) in tumor tissues and also enhanced the expression of CD80 and CD40 on pDCs, which suggest the activation of pDCs." (PMID 31849942, 2019). "The TNFR superfamily proteins are expressed by antigen-presenting cells (APC) or tumor cells, including TNFSF4 (OX40L), TNFRSF5 (CD40), TNFSF7 (CD70), TNFSF9 (CD137L), TNFRSF14 (HVEM), and TNFSF18 (GITRL)." (PMID 30609841, 2019). "SBRT and anti-CD40 administration alone each provided some local control of the treated tumor, but complete regressions of the contralateral tumors were only observed in mice receiving combination SBRT and anti-CD40." (PMID 30245691, 2018). "It was shown that TADCs modified with CD70 and simultaneously activated via CD40 and TLR4, were able to migrate to tumor draining lymph nodes and stimulate tumor-specific CD8+ T cells." (PMID 30233579, 2018). "Overall, despite the observation that IL-2/CD40 alleviates certain suppressive functions in elderly tumor-infiltrating CD8+ T cells, these cells also demonstrated reduced anti-tumor effector function." (PMID 30560130, 2018).